NLRP3 (NLR family pyrin domain containing 3)
Diseases named in the same sentence as NLRP3 in open-access papers (continued):
Sharing a sentence is not in itself a finding about the gene and the disease.
fungal infections (36 papers, 2010 to 2025). "In terms of human genetic evidence, several polymorphisms in the Nlrp3 gene have been shown to influence susceptibility and severity of fungal infections by modulating inflammasome activation and IL-1β production." (PMID 41249509, 2025). "NLRP3 defects are therefore associated with a poor prognosis upon fungal infection, ranging from severe susceptibility in invasive candidiasis to milder susceptibility to cryptococcosis." (PMID 33380899, 2020). "Both K+ efflux and ROS are the main cellular disturbances associated with NLRP3 activation in phagocytes infected with diverse fungi, encompassing those causing dermathophytoses, and invasive mycosis." (PMID 29209318, 2017). "NLRP3 inflammasome, the most studied and the main inflammasome associated with fungal infection, is activated by a typical two-step mechanism: priming and activation." (PMID 29209318, 2017). "The critical role of IL-1β in controlling C. neoformans and other pathogenic fungal infections through the activation of the NLRP3 inflammasome has recently been documented (46, –, 48)." (PMID 27165801, 2016). "Though, a crucial venture might an increased risk of opportunistic or invasive fungal infections, especially in immunocompromised patients, since the NLRP3 inflammasome plays a key role in immune defense against pathogens." (PMID 41019046, 2025). "Among the different inflammasomes, the NLRP3 is the main one associated with fungal infection." (PMID 41249509, 2025). "NLRP3-mediated pyroptosis is involved in the repair of radiation and immune damage, and the associated signal transduction pathway plays an important role in fungal infections." (PMID 35761358, 2022). "Among the inflammasomes, the NLRP3 inflammasome is the main one associated with fungal infection." (PMID 26204108, 2015). "The production of pro-IL-1β and the release of mature proinflammatory cytokines by the NLRP3 inflammasome during fungal infection can involve crosstalk with other fungal-sensing receptors." (PMID 41062723, 2025). "Nevertheless, secretion of IL‐1β during fungal infections involves collaboration between NLRP3 and CLRs since the SYK‐CARD9 pathway is required for the production of pro‐IL‐1β, and for the activation step of the inflammasome following its assembly." (PMID 36114607, 2023). "During fungal infection, the NLRP3 inflammasome formation in immune cells leads to the activation of CASP1, which then cleaves the proinflammatory cytokines IL-1β and IL-18 to their bioactive forms and induces pyroptosis." (PMID 35463001, 2022). "Among the inflammasomes, the NLRP3 inflammasome is the most well-studied inflammasome related to fungal infection." (PMID 35463001, 2022). "Innate immune sensor Z-DNA binding protein 1 (ZBP1) is the apical sensor of fungal infection and controls the NLRP3 inflammasome to participate in pyroptosis." (PMID 36311726, 2022). "During fungal infection, the activation of the NLRP3-ASC-CASP1 inflammasome leads to cleavage of pro-CASP1, which then processes the proinflammatory cytokines IL-1β and IL-18 to their bioactive forms and cleaves GSDMD to trigger pyroptosis." (PMID 35463001, 2022). "Multiple lines of evidence indicate that NLRP3 inflammasome-mediated inflammatory responses are of great importance in the control of bacterial and fungal infections." (PMID 36293012, 2022). "NLRP3 inflammasome activation has been demonstrated to contribute to host defense against diverse fungal infections, including C. albicans, A. fumigatus and P. brasiliensis, H. capsulatum, S. schenckii infection." (PMID 34912336, 2021). "The NLRP3 inflammasome is critical for host immune defenses against bacterial, viral, and fungal infections." (PMID 35002723, 2021). "Precise regulation of NLRP3 activity is thought to be critical in fungal infections and it needs to be carefully balanced." (PMID 32750090, 2020).
fungal infections (continued). "Restoring glucose homeostasis in macrophages reduced NLRP3 activation and production of the proinflammatory cytokine IL-1β, suggesting that metabolism regulates NLRP3 inflammasome activity in fungal infections." (PMID 32750090, 2020). "The core of the majority of the inflammasomes is the NOD-like receptor (NLR) and the NLR family pyrin domain-containing 3 (NLRP3) is the most studied in fungal infections." (PMID 33343578, 2020). "Increasing data have shown that the NLRP3 inflammasome is activated in macrophages in response to various bacterial, viral, and fungal infections." (PMID 31417575, 2019). "Followed by priming, the proteolytic cleavage of pro-IL-1β into its mature form is canonically performed by the protease caspase-1, and this process is largely dependent on the assembly of the NLRP3 inflammasome in fungal infections." (PMID 29209318, 2017). "One of the main functions of NLRP3 is to participate in IL-1β maturation which is important in the host defense against Pneumocystis and other fungal infections." (PMID 29170665, 2017). "One key aspect shown to determine NLRP3 inflammasome activation during fungal infection is morphogenesis." (PMID 29209318, 2017). "In contrast, Nlrp3−/−, Casp1/11−/−, and Asc−/− mice showed a prevalent Th2/Th3/Treg profile of response that was unable to control the fungal infection." (PMID 28740491, 2017). "Regarding fungal infections, the NLRP3 inflammasome is essential for casapase-1 activity and subsequent IL-1β release in murine and human phagocytes that are infected with C. albicans, A. fumigatus, T. schoenleinii and C. neoformans." (PMID 24340123, 2013). "In previous work, we and others have shown that the NLRP3 inflammasome is important in protecting from severe fungal infections." (PMID 22174673, 2011). "The use of NLRP3 Inhibition in fungal Infections might be benefical since targeting the NLRP3 inflammasome may dampen pathological inflammation seen during corticosteroid therapy, potentially reducing tissue damage and controlling excessive cytokine release." (PMID 41019046, 2025). "In addition to the NLRP3-dependent inflammasome, some fungal infections can induce NLR-independent, caspase-8-dependent inflammasome activation." (PMID 41249509, 2025). "Indeed, the NLRP3 inflammasome plays an important role in the clearance of bacterial, viral and fungal infections." (PMID 41062723, 2025). "Currently, specific clinical data on infection rates in patients on NLRP3 inhibitors are lacking, underscoring the need for ongoing surveillance and caution in future trials where fungal infection is a risk." (PMID 41019046, 2025). "SYK controls both pro-IL-1β synthesis and NLRP3 activation in response to fungal infection." (PMID 38992615, 2024). "NLRP3 functions as a pattern recognition receptor (PRR) that recognizes pathogen-associated molecular patterns (PAMPs) from bacterial, viral and fungal infections among others and that, together with the adaptor ASC/PYCARD protein and caspase-1, form the NLRP3 inflammasome." (PMID 39591118, 2024). "NLRP3 inflammasome activation is essential for fungal infection-induced pyroptosis in macrophages." (PMID 35463001, 2022). "Is IFN-I required for caspase-11–mediated NLRP3 inflammasome activation during fungal infection?" (PMID 33735255, 2021). "Of note, Casp-1-/- mice survived longer than Nlrp3-/- mice after fungal infection." (PMID 34912336, 2021). "Since F. pedrosoi activates the NLRP3 inflammasome in vitro, we investigated whether in vivo activation occurs and the possible role of this process in controlling fungal infection." (PMID 29209318, 2017). "Thus, both fungal form and phagocyte type are critical factors that dictate NLRP3 inflammasome activation in fungal infections." (PMID 29209318, 2017).
fungal infections (continued). "Here, the expression of NLRP3 inflammasome-associated components was concomitant with increased infiltration of PMNs but not macrophages into the lungs of mice, indicating the selective influence of NLRP3 activation on this important effector cell in fungal infections." (PMID 28740491, 2017). "NLRP3 is the NLR mostly involved in the immunity against fungal infections." (PMID 28740491, 2017). "In conclusion, the application of NLRP3 inflammasome inhibitors to patients treated with corticosteroids like Dexamethasone may significantly improve their outcome as they might be well-protected against local or severe systemic fungal infections." (PMID 41019046, 2025). "Moreover, western blot analysis revealed dramatically decreased levels of pyroptosis-associated proteins ASC, cleaved CASP1, GSDMD, cleaved GSDMD, cleaved IL-1β and cleaved IL-18 in the Ad-NLRP3-shRNA group compared with the Ad-GFP-shRNA group during fungal infection." (PMID 35463001, 2022). "Syk kinase activity downstream of Card9 activation by the fungal sensor Dectin1, is required for NLRP3 activation, however, the precise mechanism of NLRP3 activation by fungal PAMPs is unclear, contributing to the bottleneck in development of new drug targets to treat fungal infections." (PMID 35663964, 2022). "NLRP3 is the most studied inflammasome-activating NLR; it is activated during bacterial, viral, and fungal infections, as well as in sterile inflammation mediated by endogenous DAMPs." (PMID 36155655, 2022). "In line with its effects on receptor signaling pathways, ibrutinib treatment generally affects neutrophil activation in response to bacterial or fungal infection, which typically engage multiple TLRs, TREM-1 and NLRP3." (PMID 34485307, 2021). "With respect to inflammasome activation upon fungal infections, only the inflammasome receptors AIM2, NLRC4 and, mainly, NLRP3, are related to engaging and triggering IL-1β caspase-dependent cleavage." (PMID 29209318, 2017). "In addition, our data show that NLRP3 inflammasome activation as well as pro-IL-1β expression relies on the Syk tyrosine kinase, which is downstream from the pathogen recognition receptor Dectin-1, reinforcing the importance of Dectin-1 in the innate immune response against fungal infection." (PMID 20368800, 2010). "In addition to the NLRP3-dependent inflammasome, some fungal infections can induce a non-canonical NLRP3 inflammasome that is caspase-11-dependent." (PMID 41249509, 2025). "These scenarios could ascribe to the possibility that NLRP3 inflammasomes instruct the trafficking and recruitment of effector CD4 T cells into the site of fungal infection (livers) while having a limited effect on CD4 T cell priming and differentiation in spleens in vivo." (PMID 34912336, 2021). "However, we did not observe an influence of the NLRP3 inflammasome on the control of the fungal infection." (PMID 29209318, 2017). "Importantly, genetic variation in PFKFB3 is correlated with differential production of IL-1β after fungal infection, suggesting the existence of bidirectional signaling events, in which PFKFB3 may also be able to regulate the activation of the NLRP3 inflammasome to drive the production of IL-1β." (PMID 34044589, 2021). "In addition, fungal zymosan and mannan stimulated the NLRP3 inflammasome to induce macrophage and DC caspase-1 activity as well as IL-1β secretion, suggesting that conserved cell wall components are responsible for the ASC and NLRP3 inflammasome activation during fungal infection." (PMID 31333658, 2019). "Thus, negative control of NLRP3 activation by NLRC4/IL1Ra reduces inflammatory response, but allows host cells to control fungal infection." (PMID 41249509, 2025).
pancreatitis (36 papers, 2014 to 2026). Inflammation of the pancreas. "Structurally and functionally, the abnormal activation of the NLRP3 inflammasome has been linked to the development of several diseases, including gouty arthritis, pancreatitis, multiple sclerosis, and Alzheimer’s disease." (PMID 39691768, 2024). "So, can inhibiting STING or NLRP3 ameliorate pancreatic and lung damage caused by pancreatitis?" (PMID 38671352, 2024). "Furthermore, the upregulation of NLRP3 signaling has been linked to the development of prostate inflammatory lesions in rat models of pancreatitis when treated with a combination of estrogen benzoate and a high-fat diet." (PMID 39769450, 2024). "For example, the cross-interaction between gut microbiota and macrophages could result in the promotion of intestinal permeability and the activation of NLRP3-dependent pyroptosis in alveolar macrophages contributes to pancreatitis-associated lung injury." (PMID 34294138, 2021). "Baicalin alleviates pyroptosis and inflammatory response in hyperlipidemic pancreatitis by inhibiting the NLRP3/Caspase-1 pathway." (PMID 40620677, 2025). "The severity of pancreatitis and the levels of NLRP3 inflammasome components were subsequently evaluated in vivo and in vitro." (PMID 40620677, 2025). "A clinical study has confirmed elevated expression of NLRP3 inflammasome components in serum samples from pancreatitis patients compared to healthy controls, with NLRP3 activation correlating positively with disease severity." (PMID 40740190, 2025). "Oxidative stress, as well as inflammatory responses mediated by the NF-κB and NLRP3 pathways, have been shown to induce pancreatitis." (PMID 39769450, 2024). "The studies on the prevention of pancreatitis further support the role of NLRP3 by using various antioxidants in animal models." (PMID 39769450, 2024). "Specifically, pro-inflammatory cytokines expressed by NF-κB, such as TNF-α, IL-6, IFN-γ, and IL-8, and innate immune cytokines released by NLRP3, such as IL-1β and IL-18, play a significant role in pancreatitis." (PMID 39769450, 2024). "It is demonstrated that the NLRP3 inflammasome is incriminated in pancreatitis onset and complications." (PMID 37743919, 2023). "Research has shown that inhibiting the NLRP3/Caspase-1 signaling pathway can alleviate pyroptosis and inflammatory response in hyperlipidemic pancreatitis models." (PMID 38125797, 2023). "MCC950 can inhibit NLRP3 inflammasome activation and significantly reduce the inflammatory response and delay the process of pancreatitis." (PMID 36327405, 2022). "The activation of NLRP3 inflammasome will deteriorate inflammation of pancreatitis, and esults in production of IL-1β, IL-18, and HMGB1, which are associated with systemic injury." (PMID 33967799, 2021). "We previously reported an increased level of IL-18 in the tissue of experimental pancreatitis, and in the current report, we showed induced NLRP3, IL-18, and eosinophils in a murine model of CP." (PMID 34183442, 2021). "In that study, the plasma-derived exosomes triggered NLRP3 inflammasome activation and pyroptosis in alveolar macrophages, thus leading to pulmonary dysfunction in the progression of pancreatitis." (PMID 32751171, 2020). "Further definitive support for the involvement of NLRP3 inflammasome in the development of lung injury secondary to pancreatitis comes from a recent study in exosome research." (PMID 32751171, 2020). "In conclusion, Nar exerts protective effects on organ injuries of Cae- and L-arg-induced pancreatitis by inhibiting oxidative stress and inflammatory response via the inactivation of NLRP3 inflammasome and upregulation of Nrf2/HO-1 expression." (PMID 29849486, 2018). "Furthermore, in pancreatitis models, circHipk3 activates the NLRP3 inflammasome by binding to miR-193a-5p." (PMID 40862743, 2025).
pancreatitis (continued). "Through P2X7R inhibitor, Zhang GX inhibited the secretion of IL-1β and IL-18 which were dependent on NLRP3 to reduce chronic pancreatic inflammation and fibrosis, which confirms the pivotal role of the NLRP3 pathway in the occurrence and development of pancreatitis." (PMID 36389791, 2022). "Moreover, Dex attenuated pancreatic inflammatory response in mice with pancreatitis by reduction in NLRP3 activation." (PMID 31383789, 2019). "The negative regulation of NLRP3 can reduce the degree of pancreatitis." (PMID 30622955, 2018). "Recently, the finding that activation of an intracellular multiprotein complex, the NOD-like receptor family, pyrin domain-containing 3 (NLRP3) inflammasome, is involved in the proinflammatory process in pancreas provides valuable insights into the pathogenesis of pancreatitis." (PMID 25214720, 2014). "In this context, there arises an interesting question required to be addressed by future work, that is, whether HRS possesses the ability to inhibit the presumed HS-induced activation of NLRP3 during the development of pancreatitis." (PMID 25214720, 2014). "Also, it was demonstrated that exosomes derived from plasma could induce pancreatitis-related lung injury by activating NLRP3-dependent focal death in macrophages within the alveoli." (PMID 41335362, 2025). "It has been reported that deletion of caspase-1, ASC or NLRP3 significantly reduced edema and inflammation of AP; previous studies also indicated that knockdown of caspase-1 significantly reduced the degree of death and inflammation of pancreatitis follicle cells." (PMID 37370098, 2023). "Thus, inhibiting the NLRP3 inflammasome pathway might be an effective treatment for patients with severe pancreatitis." (PMID 37743919, 2023). "Therefore, HDL may alleviate pyroptosis and inflammatory response in hyperlipidemic pancreatitis models by inhibiting the NLRP3/Caspase-1 signaling pathway." (PMID 38125797, 2023). "As for AP, some known extracellular NLRP3 activators like DNA, adenosine triphosphate (ATP), high mobility group box 1 (HMGB1), and nucleotide binding oligomerization domain 2 (NOD2) are all associated with the inflammation during the development of pancreatitis." (PMID 25214720, 2014). "The regulatory effects of S1P signaling on pancreatitis predominantly involve NF-κB, STAT3 phosphorylation, PERK/TXNIP/NLRP3, RhoA/ROCK, and AMPK/mTOR pathways as well as IFN-γ and TGF-β1." (PMID 39519028, 2024). "But in the models of acute hepatitis and pancreatitis, activation of NMDAR finally down-regulates NLRP3 inflammasomes via a β-arrestin-2 NF-kβ and JNK pathway." (PMID 31214158, 2019). "Moreover, the development of cerulein-induced pancreatitis conspicuously stimulated the expression of TXNIP, the critical regulator of NLRP3 activity." (PMID 25214720, 2014). "Therefore, after GQD intervention, the production of NLRP3 can be inhibited, thereby reducing the synthesis of Caspase-1 and GSDMD, lowering the release of inflammatory factors such as IL-1β and IL-18, and increasing IL-10 levels, thereby preventing the progression of post ERCP pancreatitis." (PMID 40620677, 2025).